GJD2-DT (GJD2 divergent transcript)
Gene: Long non-coding RNA gene on chromosome 15 (34,755,062 to 34,813,505, forward strand). Ensembl gene ENSG00000250007.
Gene Ontology:
Biological process: SRP-dependent cotranslational protein targeting to membrane, signal sequence recognition
Cellular component: signal recognition particle, endoplasmic reticulum targeting